TFRC (transferrin receptor)
Diseases named in the same sentence as TFRC in open-access papers (continued):
Sharing a sentence is not in itself a finding about the gene and the disease.
glioblastoma (57 papers, 2008 to 2026). The most malignant astrocytic tumor (WHO grade IV). "Enriched iron content associated with increased transferrin receptor (TfR) expression is an indicator of poor glioblastoma patient outcomes; however, the underlying contributions to tumor progression remain elusive." (PMID 40429897, 2025). "Several studies have documented that the TFRC gene is abnormally overexpressed in various human tumors, including but not limited to liver cancer, glioblastoma, and colorectal cancer." (PMID 40303995, 2025). "Functionalization with transferrin, for instance, enabled BTNPs to target the transferrin receptor (TfR), commonly overexpressed on the surface of various cancer cells, including glioblastoma multiforme (GBM)." (PMID 41012541, 2025). "Information on transferrin, ferroportin, ferroreductase, transferrin receptor, ferritin and others would have provided a more complete picture of the iron pathways in glioblastoma tumours." (PMID 40123902, 2025). "Strategies such as the SGT-53 liposome, which targets the transferrin receptor, have shown promising results in glioblastoma treatment when combined with immunotherapy." (PMID 39204355, 2024). "Glioblastoma cells have a high level of the cellular transferrin receptor (TfR), making it an appealing target for gene delivery." (PMID 38304326, 2023). "Other studies found that higher levels of ROS inside mitochondrial lung cells, glioblastoma, and gastric tumor cells increased the amount of LIP inside the cells through transferrin receptor (TfR); thus, enhancing the tumor cell susceptibility to Vit-C." (PMID 35745630, 2022). "They conjugated DOX and a T7 peptide that targets brain tumor cells by binding to the transferrin receptor (TfR), often overexpressed in glioblastoma and brain capillary endothelial cells to a poly-l-lysine dendrimer loaded with the pORF-hTRAIL plasmid." (PMID 36291908, 2022). "First, the transferrin receptor is expressed on the surface of glioblastoma cells and, in particular, U-87 MG cells." (PMID 36613750, 2022). "Antisense miRNA oligonucleotides against miR-21 (AMO-21) with potential for the treatment of glioblastoma were delivered by exosomes decorated with Lamp2b-fused T7 peptide since the transferrin receptor is overexpressed on the surface of glioblastoma cells." (PMID 33304924, 2020). "Transferrin (Tr) is a natural ligand of transferrin receptor overexpressed in glioblastoma, a highly aggressive cancer with a poor prognosis." (PMID 31835371, 2019). "Fast-paced tumor replication requires high levels of iron uptake, thus TfRC is often over-expressed in breast, gastric, colon cancer and glioblastoma and has therefore prompted the use of TRC as a target for anti-cancer therapy." (PMID 18231595, 2008). "Interestingly, our results showed that in T98G glioblastoma cells, the expression of transferrin receptor 1, cystathionine β-synthase, and cysteine dioxygenase 1 (iron-dependent enzymes) is significantly increased compared to 1321N1 astrocytoma cells." (PMID 41154707, 2025). "Glioblastomas express high amounts of transferrin receptor 1, which is the main mediator of cellular iron uptake, and may also express a second transferrin receptor (transferrin receptor 2) that is not present in normal tissue." (PMID 35314642, 2022). "The brain endothelial cells and glioblastoma cells generally overexpressed a number of receptors, including the low-density lipoprotein receptor, IL-13 receptor, transferrin receptor (TfR), and nicotine acetylcholine receptor that used as drug delivery targets in the brain." (PMID 34883617, 2021).
glioblastoma (continued). "Therefore, in the future study, transferrin carried small nucleic acids like miR-124 mimics, targeting the transferrin receptor on BBB might be a potential strategy to treat glioblastoma." (PMID 39865088, 2025). "Transferrin receptor 1 (TfR1), which is highly expressed in BBB and glioblastoma cells, can mediate the transport of iron into the brain through the binding and intracellular transport of transferrin (Tf)." (PMID 39128942, 2024). "We employed here two 2′-F-RNA aptamers addressing human glioblastoma cells: GL44 aptamer, specific to U-87 MG cells, and Waz aptamer, specific to the transferrin receptor." (PMID 36613750, 2022). "Since TFRC is highly expressed in BBB vECs and brain tumors such as glioblastomas, nanoparticles targeted with TFRC-binding peptides have been explored as diagnostic probes for imaging brain tumors and for boosting brain uptake of therapeutic antibodies." (PMID 35726097, 2022). "Based on the high efficiency in glioblastoma cells, targeted delivery of RNV541 was investigated using the previously reported transferrin receptor targeting aptamer." (PMID 31284665, 2019). "Glioblastoma cancer stem cells expressed a higher level of transferrin (receptor transferrin receptor 1) than did nonglioblastoma cancer stem cells." (PMID 37433225, 2023).
brain tumors (50 papers, 2009 to 2025). "For instance, the transferrin receptor (TfR) is overexpressed in brain tumor cells as well as the BBB." (PMID 39851741, 2025). "Another receptor used to target brain tumors is the transferrin receptor (TfR), which has the role of transporting iron into cells; therefore, it is highly expressed in various body areas, including both normal brain cells and brain cancers." (PMID 40574048, 2025). "Despite these challenges, efforts continue to optimize this approach, particularly the use of cellular receptor ligands such as transferrin receptor 1 (TfR1) to effectively target brain tumor cells." (PMID 39061967, 2024). "For the active transferrin receptor–based administration of docetaxel (DTX) for the treatment of brain tumours, TPGS micelles were created." (PMID 38558360, 2024). "Delivery of DTX via the transferrin receptor can significantly improve the drug’s targeting ability in animals with brain tumours, enhancing therapeutic efficacy while minimizing the adverse effects." (PMID 38558360, 2024). "The RGD peptide can recognize the αvβ3 receptor overexpressed on neurovascular endothelial cells and the Lf can recognize transferrin receptor (TFR) on the brain tumors to facilitate the nanoparticles crossing the BBB and then targeting tumor cells." (PMID 36597214, 2023). "An appropriate example is the transferrin-based NPs that have elicited tremendous abilities to cross the BBB/BBTB by targeting the transferrin receptor-mediated transcytosis (see also Section 4.4.1) for brain tumor therapy." (PMID 36358807, 2022). "This nanosystem was modified with peptide HAIYPRH (T7), a transferrin receptor-specific peptide, for brain tumor cells targeting." (PMID 32194864, 2020). "The reported brain tumor targeting moieties include transferrin receptor (TfR), angiopep-2 peptide, TAT peptide, RGD peptide, chlorotoxin and so on 30-32." (PMID 32194864, 2020). "Drug delivery strategies that use anti-transferrin receptor antibodies have shown increased drug brain penetration in models of neurodegenerative diseases and brain tumors." (PMID 33390965, 2020). "PMLA-based nanotherapeutics target brain tumors by crossing the BBB using transferrin receptor (TfR)-mediated transcytosis." (PMID 31462642, 2019). "In another study, the iron-transport protein transferrin was labeled with 89Zr to be applied in brain tumor imaging as well as in imaging of transferrin receptor expression." (PMID 23736785, 2013). "For example, brain tumors might benefit from the combination of transferrin receptor targeting (via the OX-26 antibody) and magnetic guidance to overcome blood–brain barrier limitations." (PMID 40649300, 2025). "The typical receptors utilized in nanoparticle-based drug delivery for brain tumors includes transferrin receptor mediated transcytosis, low-density lipoprotein receptor-mediated transcytosis, insulin receptor-mediated transcytosis and nicotinic acetylcholine receptor-mediated transcytosis." (PMID 39998776, 2025). "The transferrin receptor (TfR) is highly expressed in the capillary endothelial cells of the BBB and various brain tumors, making it a significant target for receptor-mediated delivery systems." (PMID 40142943, 2025). "Both brain tumor cells and blood–brain barrier (BBB) vascular endothelial cells express certain receptors, such as the transferrin receptor (TfR) and nucleolin." (PMID 38675202, 2024). "Here, we report the best-studied and promising receptors for brain tumor delivery, including the epidermal growth factor receptor (EGFR), transferrin receptor (TfR), insulin receptor (IGFR) and lipoproteins." (PMID 36839827, 2023). "We investigated the mRNA levels of hepcidin (HAMP), HFE, neogenin (NEO1), transferrin receptor 1 (TFRC), transferrin receptor 2 (TFR2), and hemojuvelin (HFE2) in normal human brain, brain tumors, and astrocytoma cell lines." (PMID 19386095, 2009).
brain tumors (continued). "The present study describes the expression of several iron-related genes including hepcidin (HAMP), HFE, neogenin(NEO1), transferrin receptor 1 (TFRC), transferrin receptor 2 (TFR2), and hemojuvelin(HFE2) in normal human brain, brain tumors, and astrocytoma cell lines." (PMID 19386095, 2009).
iron overload (46 papers, 2009 to 2026). "As this alteration occurs in the interaction domain with transferrin receptor 1 (TfR1), it can cause a slight loss of function and, consequently, iron overload." (PMID 41157574, 2025). "However, recent studies have indicated that TFRC might exert dual effects on iron metabolism, namely, TFRC could cause iron overload and might also promote iron clearance when iron overaccumulation occurs in the brain after ischemic stroke." (PMID 40552324, 2025). "Elevated soluble transferrin receptor (sTfR) further enhances iron uptake, leading to iron overload reflected by increased ferritin levels." (PMID 41517557, 2025). "Iron overload is the result of synergistic action of multiple pathways, with the central mechanism being excessive iron uptake mediated by transferrin receptor (TfR) and divalent metal transporter 1 (DMT1)." (PMID 40287631, 2025). "Iron overload was found to be due to abnormalities in transferrin receptor (TFR1) recycling and reduction of its palmitoylation." (PMID 30744104, 2019). "The expression of transferrin receptor was decreased, and expressions of ferritins (heavy and light chains) were increased, which are consistent with myocardial iron overload." (PMID 29208771, 2018). "Expression at the gene and protein level of CD71, transferrin receptor, was of particular interest as SOD2 deficient cells, similar to sideroblasts in patients with SA, show iron overload in the presence of an obvious defect in iron utilization." (PMID 21326867, 2011). "Other blood markers, such as transferrin saturation and soluble transferrin receptor, have proven to be even less successful in establishing the diagnosis of iron overload." (PMID 19852846, 2009). "This suggests that despite the reduction of Transferrin Receptor 1, alternative pathways may effectively mediate re-absorption of iron that cycles through the kidney during parenterally induced iron-overload." (PMID 30321179, 2018). "The HFE protein was reported to be capable of forming a stable complex with transferrin receptor (TFR) to inhibit the abnormal up-regulation of the level of iron in cells, whereas the HFE C282Y mutation impairs the process and leads to peripheral iron overload." (PMID 27657935, 2016). "Mechanistically, we show that transferrin receptor 1 (TfR1) and ferritinophagy are involved in PRV-induced iron overload." (PMID 40891826, 2025). "Iron supplementation was started empirically, but iron studies, including soluble transferrin receptor (sTfR), were not available to rule out iron overload." (PMID 40842790, 2025). "However, TFR1 and DMT1 are negatively regulated by the serum iron level; this means when serum iron increases, transferrin receptor expression decreases to protect the myocardium from iron overload." (PMID 36139417, 2022).
lung carcinoma (45 papers, 1997 to 2025). "Attached to the outer surface of drug-loaded EVs is the transferrin ligand for targeting transferrin receptor (TfR) overexpressing lung cancer cells." (PMID 41551607, 2025). "In lung cancer cells, ferroptosis upregulation suppresses the cell growth by TFRC-related signaling pathway." (PMID 39251905, 2024). "LINC00597 upregulates TFRC expression by sponging hsa-miR-367-3p, thereby promoting ferroptosis in lung cancer cells." (PMID 39104501, 2024). "These nanomaterials are capable of selective attachment to the transferrin receptor (TfR) expressed on lung cancer cells, as well as accurately modulating drug release based on the pH levels and the quantity of reactive oxygen species." (PMID 36014474, 2022). "In cancer cells, iron is mainly imported via the TFRC, and this transmembrane receptor has been found to be overexpressed in many types of cancers, such as brain, breast, colon, ovarian, and lung cancers, as well as in leukemia." (PMID 36291834, 2022). "All these data suggested that TFRC and VDAC were closely associated with the survival of lung cancer patients and can be used as potential therapeutic targets in lung cancer." (PMID 34093811, 2021). "In a nutshell, the transferrin receptor plays an important role in the abnormal iron metabolism of lung cancer cells." (PMID 35082668, 2021). "To actively target lung cancer cells, we have developed a conjugate of the apoptosis inducing protein cytochrome c with transferrin because the transferrin receptor is overexpressed by many rapidly dividing cancer cells." (PMID 29649293, 2018). "Confocal results demonstrated the cellular uptake of the cytochrome c-transferrin conjugate by transferrin receptor overexpressing A549 lung cancer cells." (PMID 29649293, 2018). "However, the expressions of other receptors (AXL, BSG, KREMEN1, and TFRC) were significantly down-regulated in lung cancer patients." (PMID 38034398, 2023). "Iron has been shown to preferentially accumulate in lung cancer tissue, as these tumors have a phenotype characterized by increased iron import through the transferrin receptor (TfR), altered iron regulatory protein (IRP1/2) activity, and decreased iron export through ferroportin." (PMID 38001858, 2023). "Third, there are reports of increased transferrin receptor expression on lung cancer cells, which could limit the use of radiolabelled transferrin as a negative control." (PMID 32887739, 2020). "Moreover, targeting TFRC attenuates ferroptosis sensitivity in lung cancer." (PMID 39251905, 2024). "The top 10 proteins (MIG6, GAPDH, NDRG1_pT346, BRD4, CD26, TFRC, INPP4B, GSK3ALPHABETA, IGFBP2, and DUSP4) were screened by applying the WBFS algorithm, and they can be regarded as the candidate biomarkers that are most closely associated with the classification of lung cancer subtypes." (PMID 37509950, 2023). "Multiple under-expressed proteins were also predictable to a great extent, the top-performing ones being CASP8, MET, BCL2, and SETD2 in BRCA; AR and TFRC in gastric cancer; and VHL in lung cancer with AUCs ranging 0.814–0.866." (PMID 38491101, 2024). "In lung cancer patients, the average expression of AXL, BSG, KEEMEN1, and TFRC was very low compared to controls." (PMID 38034398, 2023). "For example, in lung cancer cells, the inhibition of cysteine desulphurase (NFS1) will up-regulate the expression of transferrin receptor TFRC, thus accelerating iron ion absorption and precipitating ferroptosis." (PMID 36237575, 2022). "Our results revealed that the expression levels of TFRC and VDAC were positively and negatively correlated with the survival of lung cancer patients, respectively." (PMID 34093811, 2021). "We analyzed the gene and protein expression of TFRC and VDAC in lung cancer patients through the UALCAN database." (PMID 34093811, 2021). "Transferrin receptor, FRA, EGFR, integrins, and CD44 are common receptors that have been explored for targeted nanoparticle-based gene delivery in lung cancer." (PMID 28290155, 2017).
lung carcinoma (continued). "Transferrin receptor protein 1 (TFR1) is highly expressed in 88% of NSCLCs, which suggests that lung cancer cells could increase iron intake by enhancing the effects of the transferrin protein (TF) and TFR." (PMID 34616505, 2021). "Likewise, a study published in 2021 treated non‐small cell lung cancer with artemisinin derivatives ART and DHA that upregulated transferrin receptor (TFRC) and downregulated cystine/glutamate transporter (xCT) which are positive and negative mediators of ferroptosis, respectively." (PMID 40377005, 2025). "In the lung cancer group, PRKG2 exhibited significant positive correlation with NFE2L2, SLC40A1, TFRC, and significant negative correlation with CHAC1 and HSPB1." (PMID 39744538, 2024).